BRAF (B-Raf proto-oncogene, serine/threonine kinase)
Diseases named in the same sentence as BRAF in open-access papers (continued):
Sharing a sentence is not in itself a finding about the gene and the disease.
cancer (continued). "Indeed, besides its well-documented prognostic role, BRAF mutations are emerging as crucial predictive markers in personalized cancer therapy." (PMID 33260892, 2020). "Interestingly, especially in the context of highly methylated BRAF mutant cancers, the loss of MEN1 has been associated with aberrant DNMT1 activity and an altered DNA methylation landscape." (PMID 32384699, 2020). "To illustrate, MSI positive stage II and III patients with double wild-type cancers had a 5-year cancer-specific survival of 93% (95% CI 84–100%); while, patients with cancers harboring mutations in either BRAF or KRAS had a 5-year cancer-specific survival of 76% (95% CI 67–85%)." (PMID 32458162, 2020). "However, the present study has confirmed that a minority of BRAF mutant cancers do carry a truncating APC mutation." (PMID 32384699, 2020). "More than 40 diverse mutations have been determined within the BRAF gene in human most cancers." (PMID 33247675, 2020). "Mutational activation of BRAF contributes to constitutive activation of NF-κB, the key transcriptional factor that controls the production of many cytokines, including IL-1β, and is usually activated by chemotherapy and in cancer drug resistance." (PMID 33396632, 2020). "There are more than 40 different types of BRAF mutations occuring in cancers." (PMID 33247675, 2020). "Mutation of BRAF gene led to uncontrollable cell growth and ultimately developed to cancer cell." (PMID 33162799, 2020). "Furthermore, even BRAF-mutated cancers develop adaptive resistance to these drugs after 6~10 months treatment by either activating Ras or alternatively splicing BRAF mutant." (PMID 32807225, 2020). "By inclusion of a smMIP targeting BRAF in the assay, these 14 samples were found to have c.1799T>A variant allele frequencies (VAFs) >5%, a threshold generally considered to be clinically relevant in cancer diagnostics." (PMID 31471937, 2020). "This may explain why precancerous lesions with both APC mutation and BRAF mutation are rarely identified, and why the cancers with these mutations present at a younger age." (PMID 32384699, 2020). "Overall, 99% of these genes were more frequently mutated in BRAF mutant cancers." (PMID 32384699, 2020). "The most frequently mutated genes are markedly different in BRAF wild type cancers." (PMID 32384699, 2020). "Thus, the prevalence of cancer (81% in 430 cases) and the proportion of BRAF (83% in 293 mutation-positive specimens) were very high, compared to other studies (cancer prevalence of 15–35%)." (PMID 32781560, 2020). "Anti-BRAF targeted therapy is the primary treatment for V600E-mutated cancers." (PMID 32411601, 2020). "Truncating mutation was present in 20% of BRAF mutant cancers." (PMID 32384699, 2020). "Here, we evaluate the mutational landscape of WNT signaling regulators in BRAF mutant cancers." (PMID 32384699, 2020). "Given its role in cell growth and division, BRAF is frequently mutated in many different cancers." (PMID 32163442, 2020). "Truncating RNF43 mutations may alter WNT signaling, but these are predominantly present in mismatch repair deficient BRAF mutant cancer, and there is controversy as to whether RNF43 mutation affects canonical WNT signaling." (PMID 32384699, 2020). "Here, we have shown that within cancers that bear BRAF mutation, the mutually exclusive nature of mutations in these genes remain, indicating that the mutual exclusivity is likely between APC and RNF43 mutations, rather than between BRAF mutations and APC mutations." (PMID 32384699, 2020).
cancer (continued). "It is possible that certain age-related genes, such as immune response-associated genes, may cooperate with BRAF-V600E in conferring poor prognosis, as BRAF-V600E was shown to be associated with abnormal immune response in human cancers, including PTC." (PMID 31897179, 2020). "However, non-V600 BRAF mutations are also relevant in several cancer types and lead to the oncogenic activation of the RAS/RAF pathway." (PMID 33081092, 2020). "KRAS and BRAF are common sites of somatic mutations in many types of human cancers, especially CRC." (PMID 31859449, 2020). "We have identified a hotspot mutation in MEN1 that effects 4% of BRAF mutant cancers." (PMID 32384699, 2020). "In addition, BRAF-mutated metastases overproduced myo-inositol, a precursor used in cancer cells for the synthesis of phosphoinositides, messengers involved in the phosphoinositide signaling system." (PMID 31744229, 2019). "However, BRAF mutation plays a crucial role in human cancer, and about 7% of all cancer cases carry this mutation." (PMID 30893857, 2019). "Correlations between cancer stem cell marker expression and BRAF V600E mutation status." (PMID 31428052, 2019). "BRAF mutation cancers were associated with worse overall survival than wild-type cancers." (PMID 31072372, 2019). "Mutated BRAF is a major driver gene alteration in cancers of multiple tissue origins." (PMID 31426419, 2019). "Vemurafenib is a BRAF inhibitor used to treat patients with BRAF V600E-mutated cancer." (PMID 30984614, 2019). "A recent experience demonstrated that genomic analysis is highly informative for some cancers with targetable mutations (e.g., BRAF and EGFR), but remains insufficient to identify effective therapeutic options for the majority of patients with advanced cancers, including PDA." (PMID 31195689, 2019). "Apart from the BRAF mutation, the most common CNVs associated with gene dysregulation were located at the 1q21 locus, which has been previously identified to be associated with cancer progression." (PMID 31443155, 2019). "Moreover, the effects of those inhibitors on downstream signalling in cancer cell lines harbouring BRAF, KRAS, or EGFR mutations were evaluated to assess the relationship between dimerization and paradoxical activation." (PMID 30679688, 2019). "Over 100 unique mutations in the BRAF gene have been identified in cancer." (PMID 31466300, 2019). "A total of 120 patients with refractory cancer who harbored BRAF mutation received vemurafenib." (PMID 31032221, 2019). "These BRAF mutant cancers have been associated with poor patient prognosis." (PMID 30975211, 2019). "We then focused on the clinical implications of the BRAF K601E alteration, as this is the most common (and only recurrent) mutation in human cancer of the non-V600 alterations that we identified, and its sensitivity to current RAF inhibitors is unknown." (PMID 31158244, 2019). "In this external validation study of previously proposed molecular subtype classifications for the prediction of survival among CRC patients, we found that MSS cancers with BRAF or KRAS mutations generally conferred a worse prognosis compared to tumors with no such mutations." (PMID 31296182, 2019). "In this guideline, we generically name EGFR mutation, ALK translocation, ROS1 translocation, and BRAF mutation as driver oncogenes that might be the direct cause of cancer evolution." (PMID 31049758, 2019). "In addition to well-characterized mutations in classes 1 to 3, we have also detected 66 novel BRAF mutations which would need further functional characterization to understand their role in cancer development and treatment response." (PMID 31470866, 2019).
cancer (continued). "BRAF mutations have been identified as targetable, oncogenic mutations in many cancers." (PMID 31466300, 2019). "BRAF mutations are frequent events in many different cancer types." (PMID 31723142, 2019). "Moreover, the cancer genome atlas (TCGA) analysis shows high BRAF mutation rate in PTC compared to FTC tumors." (PMID 30760304, 2019). "BRAF is a gene that codes for B- Raf, a proto oncogene that is mutated in many human cancers." (PMID 31277040, 2019). "As an example, IDH- and BRAF mutations are sporadically found in other cancers too." (PMID 31747973, 2019). "Similarly, other studies have shown the promising combinational effect of BRAF inhibitors and chloroquine in BRAF-mutated cancers." (PMID 31416288, 2019). "Many polymerase chain reaction (PCR)-based techniques, including traditional bidirectional direct (Sanger) sequencing, pyrosequencing, high-resolution melting analysis, PCR clamping and allele-specific PCR (AS-PCR), have been utilized to detect these BRAF mutations in human cancer specimens." (PMID 29879227, 2018). "BRAF encodes for a serine/threonine kinase that is commonly activated by a hotspot V600E somatic point mutation and represents one of the most frequently mutated genes in cancer." (PMID 29556019, 2018). "The A allele was also overrepresented in BRAF mutant cancers with MLH1 loss." (PMID 29304767, 2018). "More recently, it has been shown that the combination of dabrafenib and trametinib treatment decreased ERK activation, cell proliferation and induced apoptosis in human cancer cell lines harboring non-V600 BRAF mutations, which accounts for approximately half of BRAF-mutated NSCLC." (PMID 29455659, 2018). "Metabolic reprogramming is as a hallmark of cancer, and several studies have reported that BRAF and KRAS tumors may be accompanied by a deregulation of cellular metabolism." (PMID 29907857, 2018). "Therefore, it is unreasonable to exclude a priori that two clones of the same cancer acquire the BRAF-V600E mutation independently." (PMID 29426936, 2018). "The similarity of mutational profiles to other cancer types in cluster V suggests that they may be responsive to the same targeted treatment, such as BRAF inhibitors, provided the targeted gene or pathway is mutated." (PMID 30341300, 2018). "Other studies have hypothesized that the pathways of development differ between high-MSI cancers with BRAF mutations and microsatellite-stable cancers with BRAF mutations." (PMID 30071442, 2018). "Moreover, in nearly 7% of all cancers, mutations in the BRAF gene leads to MAP kinase pathway over-activation." (PMID 29565994, 2018). "In addition to RAS, activating mutations in the BRAF gene have been found in 8–10% of CRC cancers, and they are almost always mutually exclusive with KRAS mutations." (PMID 29881714, 2018). "Elevated levels of CA 19-9 were associated with a particularly impaired OS in BRAF-mutant cancers." (PMID 29872151, 2018). "To assess whether our filtering strategy retained known somatic mutations, we tested the impact of this strategy on the hotspot mutations in five known cancer-associated genes: BRAF, RAS family (HRAS, NRAS, and KRAS), and stop-gain NF1 gene mutations." (PMID 30662871, 2018). "BRAF, a serine/threonine kinase that is commonly activated by somatic point mutations in human cancer, could provide new therapeutic opportunities for NEC." (PMID 30559933, 2018). "One hundred ninety-five cancer samples had BRAF mutations, while 160 samples were wild-type." (PMID 30558624, 2018). "This has been demonstrated by loss of heterozygosity analysis at key loci where deletion events associated with late- compared to early-stage BRAF mutant/MSS cancers overall and at loci on 5q, 17p, and 18q, and loss at 18q and 8p correlated with worse survival." (PMID 30598662, 2018). "BRAF V600E and V600K, most commonly observed mutations in these cancers, may predict response to targeted therapies." (PMID 29879227, 2018).
cancer (continued). "This indicates that CIN contributes to progression of disease and may relate to the poor outcomes associated with BRAF mutant/MSS cancers." (PMID 30598662, 2018). "Interestingly, TERTp mutations were widely reported as associated with the presence of the BRAF V600E mutation in human cancers, mainly in TC and melanoma." (PMID 30200646, 2018). "Therefore, further investigation of the comparative efficacy of various MEK inhibitors in BRAF-mutated cancers would help to explain these contradicting results." (PMID 28947956, 2017). "Additionally, INTS11 knockdown diminishes the MAPK responsiveness and cellular growth in A375 and A549, cancer cell lines with activating mutations in BRAF and KRAS, respectively." (PMID 28982763, 2017). "The BRAFV600E mutation accounts for approximately 90% of the BRAF mutations found in cancer." (PMID 28282860, 2017). "Also, mutations in BRAF, particularly those involving the Valine600 codon, are found at very high percentages in several cancers." (PMID 28241486, 2017). "In addition, the BRAF K601E mutation needs to be considered separately because of its low probability of being associated with cancer: 3/4 BRAF K601E-mutated nodules in our series were benign." (PMID 29085338, 2017). "The V600E mutation of BRAF (in which a valine is substituted for a glutamic acid at codon 600) was discovered as an oncogenic driver mutation in 2002 when this mutation was observed in different cancers." (PMID 28418885, 2017). "The mutated BRAF is V600E in 70–80% of all BRAF mutations in all cancers." (PMID 29229974, 2017). "In fact, more than 30 mutations of the BRAF gene associated with human cancers have been identified, many of which may be sensitive to trametinib since these show deregulated stimulation of MEK1/2." (PMID 28157711, 2017). "In addition, the PNA probe design can be modified in the detection of other somatic mutations, such as EGFR, KRAS, or BRAF mutations in many cancers." (PMID 29104223, 2017). "The ERK pathway is the major deregulated pathway associated with BRAF-mutated cancers." (PMID 28947956, 2017). "Finally, we examine the effects of clinically relevant doses of Dabrafenib and/or Trametinib on HEK293T cells co-expressing mutant BRAFs with wt-CRAF and human cancer cell lines harboring non-V600 BRAF mutations." (PMID 28947956, 2017). "However, previous series have shown that CRC cells harboring KRAS mutations have a higher lung tropism than wild type or cancer cells harboring BRAF mutations." (PMID 27911859, 2017). "The V600E mutation in BRAF results in this signaling pathway being activated even in the absence of the cytokine, hormone, or growth factor stimulation, leading to unregulated cell proliferation and ultimately cancer." (PMID 28282860, 2017). "The BRAF gene is coding for a kinase that is activated by somatic point mutation in human cancer." (PMID 28918496, 2017). "Consequently, MSI testing was performed directly by the molecular cancer genetics platforms for patients under 60 years old and/or BRAF-mutated CRC when there was KRAS/BRAF testing." (PMID 29137623, 2017). "Peculiar morphological findings have been described in other BRAF-driven mutated cancers." (PMID 27738305, 2017). "Although large-scale analyses unveiled frequently altered driving mutations in many cancer types, such as BRAF (V600E) in melanoma and colorectal cancer, finding less frequently altered mutations is a challenge using large-scale analyses, especially in uncommon cancer types." (PMID 26925973, 2016). "Heterozygous loss of the RNF43 and ZNRF3 loci were identified in BRAF mutant/MSS cancers." (PMID 27661107, 2016). "RNF43 was commonly mutated in BRAF mutant cancers compared to BRAF wild type cancers." (PMID 27661107, 2016). "An RNF43 frameshift mutation (X659fs) occurred in 80% BRAF mutant/MSI cancers." (PMID 27661107, 2016). "Missense mutations in the BRAF gene contribute to the incidence of various types of cancer." (PMID 27094161, 2016).
cancer (continued). "BRAF genetic missense mutations are associated with the incidence of various types of cancers." (PMID 27094161, 2016). "Considering that sorafenib is able to induce clinical response in about 30 % of HCC patients, it could be worth verifying the real frequency of BRAF mutations in this type of cancer, and whether a higher frequency of mutation is related to sorafenib response." (PMID 27388325, 2016). "The association of BRAF mutant genes with increased autophagic activity was exploited towards establishing novel as well as efficient anti-cancer treatment protocols, which involve either inhibitors of autophagy as a single agent treatment or their rational combination with BRAF600E targeting drugs." (PMID 26802026, 2016). "The BRAF V600E mutation gene has been reported to promote cancer cell survival and proliferation." (PMID 26884744, 2016). "In addition, SSA/Ps exhibit a high frequency of gain-of-function mutations in the BRAF gene, ranging from 70% to 100%9‐13; BRAF mutations have been implicated in a variety of cancers due to their activation of the MAPK signaling pathway." (PMID 28430953, 2016). "Since the genomic alterations close to the root node are genes frequently mutated in cancers, such as BRAF, which should be of better clinical potential, we then narrowed down those genomic alterations by optimally selecting the alterations associated with the first node of the tree." (PMID 26916442, 2016). "RNF43 was frequently mutated in BRAF mutant/MSI cancers (47/54; 87.0%)." (PMID 27661107, 2016). "The same BRAF mutation is found in nearly all of these cancers." (PMID 26744778, 2016). "PIK3CA mutations frequently coexist with RAS and BRAF mutations in patients with advanced cancers." (PMID 27276710, 2016). "There are two main hotspot regions for cancer-causing mutations in BRAF." (PMID 26744778, 2016). "Overall, these results suggest that ReKINect is capable of predicting NAMs that constitutively activate or inactivate protein kinases and that, in addition to BRAF V600E, numerous other similar mutations are likely to exist that directly affect the catalytic activity of kinases in cancer signaling." (PMID 26388441, 2015). "Although the BRAF mutation can be a promising molecular marker for these cancers, detection of the mutation in urine may be challenging due to several reasons." (PMID 29061943, 2015). "Moreover, it had received much more attention these years because of its high frequency of KRAS and BRAF mutations identified in certain human cancers and the critical role this pathway plays in promoting cell survival." (PMID 26347850, 2015). "Since activating BRAF mutations are present in a wide variety of human cancer, we hypothesized that BRAF gene mutations are similarly involved in canine cancers, leading to hyperactivation of the MAPK pathway and cell transformation." (PMID 26053201, 2015). "Several early, somatic, or activating mutations in the BRAF oncogene cause the protein to become hyperactive, releasing a cascade of signals which may play an important role in some specific malignant tumours." (PMID 25932044, 2015). "The preclinical experiments demonstrated trametinib had broad anticancer activity in multiple cancer models by inducing cell cycle arrest, apoptosis and growth inhibition in vitro and in vivo, especially in cancer cells with activating mutations of BRAF and KRAS in the MAPK pathway." (PMID 25915534, 2015). "From a veterinary oncology perspective, high frequencies of the BRAF mutation in canine UC and PC may represent a promising molecular diagnostic marker and therapeutic target for these clinically challenging cancers." (PMID 29061943, 2015). "Taken together, our findings indicate that BRAF mutations are likely to stimulate proliferation and induce hyperplasia, however early lesions with mutated BRAF rarely progress to malignant disease, unless they are overlapping with other oncogenic mutations found in NSCLC." (PMID 26374070, 2015).